SLC36A4 (solute carrier family 36 member 4)
Description:
Uniporter that mediates the transport of neutral amino acids like L-tryptophan, proline and alanine. The transport activity is sodium ions-independent, electroneutral and therefore functions via facilitated diffusion.
Synonyms: PAT4; FLJ38932
Tractability: Antibody: its Gene Ontology location is reachable by antibodies, with high confidence; UniProt predicts a signal peptide or a membrane-spanning region; the Human Protein Atlas places it where antibodies can reach. PROTAC: ubiquitination databases record sites on it.
Gene: Protein-coding gene on chromosome 11 (93,144,174 to 93,197,991, reverse strand). Ensembl gene ENSG00000180773.
Subcellular location: Lysosome membrane
Subcellular location (Human Protein Atlas): Cytosol; Golgi apparatus; Plasma membrane
Pathways (Reactome):
Metabolism: Tryptophan catabolism
Transport of small molecules: Amino acid transport across the plasma membrane
Gene Ontology:
Molecular function: L-alanine transmembrane transporter activity; L-proline transmembrane transporter activity; L-tryptophan transmembrane transporter activity
Biological process: L-alanine transport; proline transport; tryptophan transport; amino acid transmembrane transport; L-proline import across plasma membrane; L-tryptophan transmembrane transport
Cellular component: lysosomal membrane; plasma membrane
Genetic constraint (gnomAD): Loss-of-function variants: 24 observed, 22.89 expected, observed/expected ratio (o/e) 1.05, 90% interval 0.76 to 1.47. The upper end of that interval is the gene's LOEUF score, 1.47, which puts it in group 6 of 6, group 1 being the genes least tolerant of losing a copy. Missense variants: 360 observed, 372.86 expected, observed/expected ratio (o/e) 0.97, 90% interval 0.88 to 1.05. Synonymous variants: 129 observed, 132.83 expected, observed/expected ratio (o/e) 0.97, 90% interval 0.84 to 1.12.
Homologues: Orthologues: macaque SLC36A4 (98% identical), chimpanzee SLC36A4 (97% identical), dog SLC36A4 (95% identical), pig SLC36A4 (94% identical), rabbit SLC36A4 (93% identical), mouse Slc36a4 (88% identical), guinea pig SLC36A4 (87% identical), rat Slc36a4 (85% identical), tropical clawed frog slc36a4 (62% identical), zebrafish slc36a4 (53% identical), Drosophila melanogaster CG13384 (36% identical), Drosophila melanogaster CG7888 (31% identical), and 15 more. Paralogues in human: SLC36A1 (51% identical), SLC36A2 (48% identical), SLC36A3 (44% identical), SLC38A3 (20% identical), SLC38A4 (20% identical), SLC38A2 (19% identical), SLC38A5 (19% identical), SLC38A1 (18% identical), SLC38A6 (18% identical), SLC32A1 (16% identical), SLC38A8 (14% identical), SLC38A10 (14% identical), and 3 more.
Diseases named in the same sentence as SLC36A4 in open-access papers:
SLC36A4 is named in the same sentence as 7 diseases in open-access papers, as found by Europe PMC text mining. Sharing a sentence is not in itself a finding about the gene and the disease. The quoted sentences say what the papers report.
colorectal cancer (4 papers, 2016 to 2019). A primary or metastatic malignant neoplasm that affects the colon or rectum. "Here, we analyse the functions of SLC36 family member, SLC36A4, otherwise known as proton-assisted amino-acid transporter 4 (PAT4), in colorectal cancer." (PMID 26434594, 2016).
brain tumor (1 paper, 2025). "We demonstrate that NR reduces brain tumor growth by downregulating the expression of the SLC36A4 amino acid transporter Path specifically in the BBB of tumor-bearing brains." (PMID 41252380, 2025).
Insulin resistance (1 paper, 2023). Increased resistance towards insulin, that is, diminished effectiveness of insulin in reducing blood glucose levels. "Further investigations are warranted to identify possible additional effects of this locus on insulin resistance, possibly via impact on SLC36A4, as well as insulin secretion through MTNR1B." (PMID 37291194, 2023).
tumor (7 papers, 2016 to 2025). "Previous studies have found that tumor cells can transport the tryptophan metabolite KYN into cytotoxic CD8+ T-cells by mediating SLC36A4." (PMID 36925967, 2023).
cancer (5 papers, 2016 to 2025). A tumor composed of atypical neoplastic, often pleomorphic cells that invade other tissues. "The SLC36A4 gene belongs to a family of amino acid transporters that have been poorly studied in cancer; however, it is well known that amino acid transport is essential for the metabolism of cancer cells." (PMID 40430005, 2025).
SLC36A4 also shares sentences with these, for which no sentence is quoted: colorectal tumours (1 paper); renal carcinoma (1).